GPR65 (G protein-coupled receptor 65)
Diseases named in the same sentence as GPR65 in open-access papers (continued):
Sharing a sentence is not in itself a finding about the gene and the disease.
Acidosis (4 papers, 2013 to 2020). Abnormal acid accumulation or depletion of base. "Acidosis activates a family of proton sensing G-protein coupled receptors, including G-protein coupled receptor 4 (GPR4), G-protein coupled receptor 65 (GPR65), G-protein coupled receptor 68 (GPR68), and G-protein coupled receptor 132 (GPR132)." (PMID 25988385, 2015).
bone cancer (4 papers, 2015 to 2019). A primary or metastatic malignant neoplasm affecting the bone or articular cartilage. "Neuronal expression of GPR65 has been shown to increase in murine models of bone cancer pain and following carrageenan- or CFA-induced inflammation, and when siRNA targeting GPR65 is administered to animals before the induction of these models less mechanical hyperalgesia is observed." (PMID 31544616, 2019).
breast tumor (4 papers, 2010 to 2025). "First, we examined the expression of different acid sensors in human breast tumor specimens compared with normal mammary tissue and identified OGR1 (GPR68) and TDAG8 (GPR65) as being highly expressed in different subtypes of invasive breast carcinomas." (PMID 35545051, 2022).
leukemia (4 papers, 2015 to 2025). A malignant (clonal) hematologic disorder, involving hematopoietic stem cells and characterized by the presence of primitive or atypical myeloid or lymphoid cells in the bone marrow and the blood. "Restoring expression of GPR65 mediates apoptosis of leukemia cells in vitro and retards leukemia expansion in vivo, indicating a tumor suppressor function of GPR65 in hematologic malignancies." (PMID 34680233, 2021).
myocardial infarction (4 papers, 2017 to 2025). Gross necrosis of the myocardium, as a result of interruption of the blood supply to the area, as in coronary thrombosis. "Additional studies showed that GPR65 alleviated myocardial infarction-induced inflammation through inhibiting resident macrophage secretion of CCL20, a chemokine for γδT cells." (PMID 39336742, 2024). "The expression of GPR65 in cardiovascular diseases confers a protective action against myocardial infarction through transcriptional downregulation of the chemokine CCL20’s expression in macrophages, which, in turn, downregulates the production of pro-inflammatory IL17A." (PMID 39336742, 2024). "It is proposed that GPR65 may serve as a pivotal regulator and therapeutic target in the context of myocardial infarction (MI)." (PMID 40563452, 2025).
spondyloarthritis (4 papers, 2017 to 2022). "Both GM-CSF+ and IL-17A+GM-CSF+ double-producing CD4 T cells express increased levels of GPR65, a proton-sensing receptor associated with spondyloarthritis in genome-wide association studies and pathogenicity in murine inflammatory disease models." (PMID 29142230, 2017). "The levels of GM-CSF-producing CD4 and CD8 lymphocytes were shown to be increased in the blood and joints of patients with spondyloarthritis, and G protein-coupled receptor 65 was found to mediate GM-CSF production." (PMID 35835809, 2022). "The upregulation of GPR65 in ex vivo sorted spondyloarthritis Th17 cells further validates a function for this receptor in driving pathogenic T cell responses in human disease." (PMID 29142230, 2017). "Next we studied expression of GPR65 in pooled Th17 cells from additional spondyloarthritis patients, healthy donors and RA disease controls." (PMID 29142230, 2017). "Here the authors show that patients with spondyloarthritis have increased numbers of GM-CSF-secreting blood and synovial lymphocytes, Th17 or not, that carry a unique transcriptional profile including enhanced GPR65 expression." (PMID 29142230, 2017). "GM-CSF and GPR65 may thus serve as targets for therapeutic intervention of spondyloarthritis." (PMID 29142230, 2017).
atopic dermatitis (3 papers, 2022 to 2024). "The GPR65 locus contains many variants other than I231L that have been associated across several autoimmune diseases including atopic dermatitis, multiple sclerosis, and IBD." (PMID 39028811, 2024). "GPR65 variants have also been linked to susceptibility and severity of ankylosing spondylitis and atopic dermatitis." (PMID 39028811, 2024). "Moreover, the recent studies found that GPR65 deficiency aggravates LPS‐induced lung injury and atopic dermatitis in mouse models." (PMID 35343079, 2022). "Multiple genome‐wide association studies have illustrated that the GPR65 locus is a risk gene for human IBD, arthristis and atopic dermatitis." (PMID 35343079, 2022).
Chronic colitis (3 papers, 2022 to 2023). A chronic inflammatory disease of the large intestine (colon, cecum and rectum). "Additionally, we performed a complementary experiment and explored whether deficiency of Gpr65 in CD4+ T cells affected the development of chronic colitis in mice." (PMID 35343079, 2022).
Chronic Lymphocytic Leukemia (3 papers, 2013 to 2024). "GPR65 gene expression also correlates with pro-survival members of the B cell lymphoma-2 (Bcl-2) family of mitochondrial proteins in chronic lymphocytic leukemia (CLL)." (PMID 39336742, 2024). "Here we are the first to report that GPR65 is expressed in primary human Chronic Lymphocytic Leukemia (CLL) cells and that GPR65 expression levels in these cells correlate strongly with expression levels of the anti-apoptotic Bcl-2 family members Bcl-2, Mcl-1, and Bcl-xl." (PMID 25984552, 2014).
colon cancer (3 papers, 2024 to 2026). "Our study found that GPR65, different from other types of cancer (colon cancer, pancreatic cancer, etc.), has a new expression feature in OS patients, and reveals that the low expression of GPR65 indicates poor prognosis in OS patients." (PMID 38218960, 2024).
glioma (3 papers, 2018 to 2025). A benign or malignant brain and spinal cord tumor that arises from glial cells (astrocytes, oligodendrocytes, ependymal cells). "In gliomas, GPR65 serves as the primary lactate receptor on TAMs, where it activates the cAMP/PKA/CREB pathway, induces high mobility group box 1 (HMGB1) secretion, and fosters glioma progression." (PMID 41152975, 2025). "Consistent with this, our study showed that among the proton-sensing GPRs, the expression of GPR65 was increased significantly in glioma compared with normal tissues." (PMID 38576043, 2024). "Blocking this feedback loop by targeting GPR65 or HMGB1 represents an attractive therapeutic option for glioma." (PMID 38576043, 2024). "GPR65, selectively highly expressed on TAMs in glioma, sensed lactate stimulation and fostered HMGB1 secretion via the cAMP/PKA/CREB signaling pathway." (PMID 38576043, 2024). "Consistent with the cellular behaviors, molecular changes related to mesenchymal transition were also reversed, characterized by decreased expression of Vimentin and N-cadherin, and increased expression of E-cadherin in glioma cells when GPR65 was inhibited." (PMID 38576043, 2024). "Based on these findings, HMGB1 emerged as a potential candidate for validating the pro-tumor effects of lactate-GPR65 signals on TAMs in glioma." (PMID 38576043, 2024). "Through subsequent functional experiments, the signaling transduction of GPR65 sensing lactate-stimulation was found it necessary for TAMs to promote glioma progression." (PMID 38576043, 2024). "Simultaneously, TAMs respond to lactate stimulation by secreting HMGB1 through the activation of GPR65, further enhancing glioma progression." (PMID 38576043, 2024). "The results revealed that the proliferative effects of lactate-stimulated shNC-TAMs on glioma cells were attenuated by GPR65 knockdown." (PMID 38576043, 2024). "Disrupting this feedback loop by GPR65-knockdown or HMGB1 inhibition mitigated glioma progression in vivo." (PMID 38576043, 2024). "Inhibiting GPR65 or targeting HMGB1 showed anti-tumor potential for glioma in models, indicating as attractive targets for glioma." (PMID 38576043, 2024). "Overall, among these receptors for lactate-stimulation, GPR65 selectively overexpressed on TAMs in glioma, revealing its potential role as mediator in regulating functional TAMs for tumor progression." (PMID 38576043, 2024). "More importantly, it was revealed that the expression of GPR65 was mainly on TAMs in glioma through analysis of scRNA-seq data and samples verification." (PMID 38576043, 2024). "Pharmacologic inhibition of GPR65 has demonstrated anti-glioma potential in preclinical models." (PMID 41152975, 2025). "Consequently, the inhibition of HMGB1 levels in CM from shNC TAMs using glycyrrhizin led to a notable reduction of tumor cell proliferation, while the exogenous addition of rHMGB1 rescued the enhanced growth of glioma cells in GPR65-silenced TAMs." (PMID 38576043, 2024). "Our analysis of glioma datasets downloaded from The Cancer Genome Atlas (TCGA) unveiled significant differences in expression patterns between normal and tumor tissues, specifically an upregulation of GPR65, and a downregulation of GPR68." (PMID 38576043, 2024). "Moreover, GPR65 was recognized as the main lactate receptor on TAMs in glioma, and its activation drives glioma progression through HMGB1 secretion via the cAMP/PKA/CREB signaling pathway." (PMID 38576043, 2024). "In conclusion, these findings collectively demonstrate that GPR65 on TAMs serves as the key sensor for lactate signaling in the tumor microenvironment, driving the malignant progression and mesenchymal transition of glioma cells." (PMID 38576043, 2024). "Furthermore, GPR65 silencing alleviated the enhanced cell migration and invasion induced by lactate-stimulated shNC-TAMs in glioma cells." (PMID 38576043, 2024).
glioma (continued). "Furthermore, a proton-sensing G-protein coupled receptors (GPRs), GPR65 was identified as the main receptor sensing lactate-signal on TAMs, mediating the protumor effects of TAMs in glioma." (PMID 38576043, 2024). "GPR65, highly expressed on TAMs, sensed lactate-stimulation in the TME, fueling glioma cells malignant progression through the secretion of HMGB1." (PMID 38576043, 2024). "Mechanistically, the lactate-signal activated GPR65 on TAMs, triggering the secretion of HMGB1 through the cAMP/PKA/CREB signaling pathway, ultimately facilitating glioma progression." (PMID 38576043, 2024). "However, whether GPR65 contribute to the process of glioma or BGM is still unclear." (PMID 30356407, 2018). "In our study, we found that GPR65+TAMs could affect the secretion of HMGB1, thereby facilitating the progression and mesenchymal transition of glioma cells." (PMID 38576043, 2024).
Lewis lung carcinoma (3 papers, 2023 to 2025). "In contrast, it has been reported that GPR65 expression enhances tumor growth in Lewis lung carcinoma cells, and that GPR65 is overexpressed in glioblastoma, which is associated with an unfavorable clinical outcome for patients." (PMID 36902589, 2023). "In tumor studies on Lewis lung carcinoma cells, GPR65 has been proven to promote cell survival and growth by activating the cAMP-ERK signaling pathway." (PMID 37723567, 2023).
multiple sclerosis (3 papers, 2018 to 2024). A progressive autoimmune disorder affecting the central nervous system resulting in demyelination. "Despite the fact that the multiple sclerosis GWAS literature does not highlight GPR65, sphingolipid metabolism has emerged as a therapeutic target for MS via the drug fingolimod, a sphingosine analog that alters immune cell trafficking and is now in clinical use." (PMID 29588361, 2018).
osteoporosis (3 papers, 2014 to 2025). A condition of reduced bone mass, with decreased cortical thickness and a decrease in the number and size of the trabeculae of cancellous bone (but normal chemical composition), resulting in increased fracture incidence. "One study ever reported that TDAG8, another name of GPR65, inhibited osteoclastic activity in osteoporosis, which supports our findings." (PMID 34485279, 2021). "As it was reported GPR65 negatively regulated osteoclastic activity in osteoporosis, it implied that GPR65 may play an important role in CRC-induced osteoclastogenesis." (PMID 34485279, 2021).
osteosarcoma (3 papers, 2024). A usually aggressive malignant bone-forming mesenchymal neoplasm, predominantly affecting adolescents and young adults. "In addition, this lower expression of GPR65 was found to be correlated with an increased risk of metastasis and poor prognosis for osteosarcoma patients, likely by suppressing immune escape and osteosarcoma cell proliferation." (PMID 39336742, 2024). "Consistent with the database results, the expression level of GPR65 in osteosarcoma patients was significantly lower than that in normal bone tissue." (PMID 38218960, 2024). "A recent single-cell RNA-Seq study indicated that the expression of GPR65 is reduced significantly in osteosarcoma." (PMID 39336742, 2024). "All these results confirmed that GPR65 plays an important role in multiple processes of osteosarcoma development." (PMID 38218960, 2024). "To further clarify the role of GPR65 in the development of osteosarcoma, we first examined the expression of GPR65 in tissue microarray of osteosarcoma and normal bone tissue." (PMID 38218960, 2024). "Overall, these results indicated that GPR65 expression was lower in younger OS patients (age ≤ 10y), metastatic osteosarcoma patients, and osteosarcoma patients with shorter survival time." (PMID 38218960, 2024). "Taken together, GPR65 expression is decreased in osteosarcoma tissues, and knocking-down GPR65 expression in osteosarcoma cells significantly promotes cell proliferation." (PMID 38218960, 2024). "Further using ROC curve to analyze the diagnostic value of GPR65 expression in terms of age in OS patients, the results showed that the area under the curve (AUC) of GPR65 gene in elderly osteosarcoma patients (age > 20 years old) was 83.30%, with statistical significance (P < 0.05)." (PMID 38218960, 2024). "Given the changes in cell morphology of U2OS and HOS cells with different GPR65 expression, we hypothesized that GPR65 may be involved in the invasion and metastasis of osteosarcoma cells." (PMID 38218960, 2024). "In contrast, GPR65 inhibits cancer progression in osteosarcoma." (PMID 39336742, 2024). "The expression of GPR65 is significantly decreased in osteosarcoma tissues." (PMID 38218960, 2024). "Silencing the expression of GPR65 in osteosarcoma cells U2OS and HOS can promote the proliferation and invasion process, while overexpression of GPR65 can inhibit this process." (PMID 38218960, 2024). "However, the expression pattern and function of GPR65 in osteosarcoma (OS) remain unclear." (PMID 38218960, 2024). "Verification experiment found that silencing the expression of GPR65 in osteosarcoma cells U2OS and HOS could promote the proliferation and invasion process, RNA-seq results showed that the role of GPR65 in OS cells was related to immune system, metabolism and signal transduction." (PMID 38218960, 2024).
Autoimmunity (2 papers, 2017 to 2024). The occurrence of an immune reaction against the organism's own cells or tissues. "GPR65, which was also validated, is also known as T cell death-associated gene 8 (TDAG8), an acidosis-sensing molecule and that has been described in association with susceptibility to autoimmunity, including in the CNS." (PMID 28279172, 2017). "Consequently, pharmacological modulation of GPR65 could benefit a broad range of pathologies, such as cancer and autoimmunity, where immune modulation is desirable." (PMID 39483470, 2024).
B-cell acute lymphoblastic leukemia (2 papers, 2025). A neoplasm of lymphoblasts committed to the B-cell lineage, typically composed of small to medium-sized blast cells. "In human patients and an immune-competent mouse model of B-cell acute lymphoblastic leukemia, low GPR65 expression correlates with resistance to CD19+ CAR T treatment." (PMID 39998425, 2025). "The study identifies GPR65 as an important determinant of B-cell acute lymphoblastic leukemia response to CAR T-cell therapy." (PMID 39998425, 2025). "Notably, GPR65 expression also influences immunotherapy outcomes: in a mouse model of B-cell acute lymphoblastic leukemia, low GPR65 expression conferred resistance to CD19 + CAR T therapy, partly by remodeling tumor–macrophage interactions." (PMID 41152975, 2025).
experimental autoimmune encephalomyelitis (2 papers, 2020 to 2024). An autoimmune demyelinating disease of the central nervous system that is produced experimentally in animals by the injection of homogenized brain or spinal cord in Freund's adjuvant. "Furthermore, this group reconstituted wild-type (WT) and GPR65-knockout (KO) CD4+ T cells into RAG-deficient mice and observed the loss of GPR65 in CD4+ T cells protected mice from experimental autoimmune encephalomyelitis (EAE)." (PMID 39336742, 2024). "Furthermore, GPR65 deletion was investigated in an experimental autoimmune encephalomyelitis mouse model." (PMID 39336742, 2024). "It was found that GPR65 is necessary for TH17 pathogenicity [GPR65 knockout mice did not develop experimental autoimmune encephalomyelitis (EAE) and did not produce IL‐17A+ cells when activated by IL‐23]." (PMID 32696457, 2020).
glioblastoma (2 papers, 2023). The most malignant astrocytic tumor (WHO grade IV). "Moreover, Lailler reported that in glioblastoma (GBM), the expression of the lactate receptor GPR65 was highest at the mRNA level." (PMID 37564659, 2023).
Hypoglycemia (2 papers, 2019 to 2021). A decreased concentration of glucose in the blood. "Given that HGP is stimulated by neural counter-regulatory responses (CRR) to hypoglycemia, we hypothesized that GPR65 vagal afferents activate the underlying neurocircuits." (PMID 34043943, 2021).
kidney cancer (2 papers, 2017 to 2025). Primary or metastatic malignant neoplasm involving the kidney. "Lastly, a significant limitation is the context-dependent duality of GPR65, functioning as potentially tumor-suppressive in some contexts (like our findings in LUAD and reports in hematologic malignancies) while appearing oncogenic in others (e.g., colon, ovarian, kidney cancers)." (PMID 40519919, 2025).
sarcoma (2 papers, 2019 to 2024). A usually aggressive malignant neoplasm of the soft tissue or bone. "Although GEPIA describes sarcoma tissue more generally, it is necessary to analyze the expression of GPR65 in a single OS tissue." (PMID 38218960, 2024). "Compared with normal tissue, higher expression of GPR65 was observed in sarcoma tissue." (PMID 38218960, 2024).
T cell lymphoma (2 papers, 2024 to 2025). "GPR65 was initially discovered as a gene highly expressed during glucocorticoid-induced apoptosis of immature thymocytes and has been mapped to chromosome 14q31-q32.1, a location at which abnormalities associated with T cell lymphoma and leukemia are found." (PMID 39336742, 2024). "The expression of GPR65 promotes the evasion of acidosis-induced apoptosis in WEHI7.2 and CEM-C7 T cell lymphoma cells under glutamine starvation conditions." (PMID 39336742, 2024).
acute lymphoblastic leukemia (1 paper, 2018). Leukemia with an acute onset, characterized by the presence of lymphoblasts in the bone marrow and the peripheral blood. "Basenji predicts the C>G at rs78461372 to increase transcription of the nearby GPR65 in many cells, most severely acute lymphoblastic leukemia cell lines, thyroid cells, insular cortex cells, and a variety of immune cells." (PMID 29588361, 2018).
adenoma (1 paper, 2023). A neoplasm arising from the epithelium. "Moreover, loss of epithelial GPR65 resulted in decreased expression of proliferative markers, including Ki67 and PCNA, in adenoma-bearing colon tissues." (PMID 37749885, 2023).